CCL5 (C-C motif chemokine ligand 5)
Diseases named in the same sentence as CCL5 in open-access papers (continued):
Sharing a sentence is not in itself a finding about the gene and the disease.
tumor (continued). "However, although expression of Ccl5 and its receptors Ccr1 and Ccr3 were not affected by IL-6Rα deficiency in CAC, expression levels of Ccl20 and of its unique receptor Ccr6 were reduced in knockout tumours." (PMID 29695802, 2018). "In addition, we sought to determine whether Ccl5 produced by non-neoplastic cells contributes to M-GBM tumor growth by comparing M-GBM cell growth in wild-type versus Ccl5−/− mouse striata." (PMID 28380429, 2017). "Other CC chemokines including CCL3, CCL4, CCL5 (RANTES), and CCL22 (macrophage-derived chemokine) and some CXC chemokines, in particular CXCL8, may also be involved in TAM recruitment, because they are highly expressed in many human tumors and various tumor cell lines." (PMID 25125485, 2014). "In addition, CCL5 secreted by CAFs promotes metastasis by activating the HIF1α/ZEB1 axis in HCC cells, whereas herbal components such as glycyrrhizic acid may inhibit the interaction of CAFs with tumour cells and reduce the release of immunosuppressive factors." (PMID 40495147, 2025). "While CCL5, CD52, DSTN and IL7R still exhibited a trend of high expression in tumour samples, but no significant discrepancy existed." (PMID 39098994, 2024). "It showed non-MDSC tumor-resident myeloid populations produced CCL5 in response to CD40 activation, but not in response to immune checkpoint blockade, and CCL5-recruitment of CD4+ T cells mediated treatment efficacy." (PMID 38786066, 2024). "Although its potential role in cancer progression has been reported in some studies of various tumor types, including CRC, the CCL5/CCR5 axis has not been extensively studied in cancer treatment, and the role of CCL5 in CRC is still controversial." (PMID 37141250, 2023). "While the increase of the expression level of dog CCL5 was not significant, the expression of dog CXCL10 was significantly different between rMV-SLAMblind-treated tumor tissue and tumor tissue from the control group (p < 0.05)." (PMID 37875555, 2023). "An increase in CCL5 and CCL17 expressions stimulated by gene electrotransfer did not affect tumor growth." (PMID 36286054, 2022). "CCL5 regulates the expression of CXCL9 (but not CXCL10) in the TAMs, thus allowing the recruitment of CD8 T cells within the tumor and tumor growth control." (PMID 36429101, 2022). "Besides, CCL5, CCL19 and CXCL9 were positively correlated with CD8+ T cell infiltration assessed by QUANTISEQ (Rho = 0.818, 0.578, and 0.716, respectively), which suggested that a high expression of CCL5, CCL19, and CXCL9 might promote the tumor infiltration of CD8+ T cells in CL-BCa." (PMID 35359417, 2022). "In addition, cytokines such as CCL5 and CXCL10 may promote cancer cell proliferation by recruiting myeloid cells, and this is essential to activate the immune checkpoint PD-1/PD-L1 axis, which establishes an immunosuppressive tumor microenvironment in multiple cancer types." (PMID 34625086, 2021). "More interestingly, IRGPI serum scores, which were calculated with the serum CCL5 and CCL25 concentrations, also showed a close-to-significant negative correlation with tumor PD-L1 IHC scores (n = 40, p = 0.058)." (PMID 34771505, 2021). "Compared with normal control tissues, the expression level of CD3D and CD2 in tumor tissues were not significantly different, while the expression levels of CD3E, CD3G, CCL5, CXCR6 and LCK in tumor tissues were lower than those in normal tissues (P < 0.05)." (PMID 34218795, 2021). "Pre-incubation with 1 μg/ml anakinra dramatically reduced the production of CXCL8 and CCL2 but not CCL5 for both UPCI-SCC90 and FaDu 3D tumour-stromal models." (PMID 35047989, 2021). "CCL5 and CCR1/CCR3/CCR5 expression correlates with tumor invasiveness, since none of these molecules are expressed in ovarian precancerous tissues but all are expressed in primary cancer and metastatic tissues." (PMID 32630699, 2020).
tumor (continued). "Similar to Ptgs1/Ptgs2−/− BRAFV600E tumors, B16-OVA tumors (that do not produce PGE2) expressing CCL5 and XCL1 showed increased accumulation of cDC1 within the TME and decreased tumor growth." (PMID 29429633, 2018). "Given the role of Ccl5 as a chemokine, it may recruit monocytes to the implantation site to facilitate tumor growth; however, we found no change in the number of recruited monocytes or chemokine expression within the tumor between the control and Ccl5 KD groups (data not shown)." (PMID 28380429, 2017). "αCD40-induced changes in tumour inflammatory mediators IL-1α, RANTES (CCL5) and GM-CSF (CSF2) at the mRNA level did not translate into significant increases in protein expression (data not shown)." (PMID 26918344, 2016). "Taken as a whole this work strongly suggests that CCL5 acts through CCR5 to promote angiogenesis, and that tumor neovascularization mediated by CCL5/CCR5 is not BM dependent." (PMID 27863423, 2016). "As assessed by qRT-PCR on tumor fragments, IR treatment increased expression of CXCL10 and CCL5, but not CCL4." (PMID 27343548, 2016). "Mechanistically, paracrine CCL5 from ovarian CSLCs activates the NF-κB signaling pathway in ovarian non-CSLCs via binding CCR1/3/5, thereby inducing EMT and tumor invasion." (PMID 25788271, 2015). "Global transcriptome studies on the spleen with and without the impact of the tumor surprisingly revealed up-regulated immune related functions in old hosts with CD2, CD3ε, CCL5, and CCL19 being key T-cell related factors." (PMID 26497558, 2015). "Positive correlation between CCL5 and VEGF versus negative between CCL5 and miR-200b indicated CCL5 promoting VEGF-dependent angiogenesis and tumor growth by down-regulating miR-200b in vivo." (PMID 25301739, 2014). "In oral squamous cell carcinoma (OSCC), the expression of MCP-1 and CCL5 have detected in scattered non-neoplastic inflammatory cells, while only a few of MCP-1 expressing tumor cells have been found in less than 40% of cases studied." (PMID 20544025, 2010). "Meanwhile, the monotherapy of HDAC1 inhibitor such as romidepsin elevated serum CCL5 rather than intratumoral CCL5, in which the systemic administration increased serum CCL5 could potentially activate metastasis-prone CCR5+ tumor cells." (PMID 40475010, 2025). "Unaltered CCL5 expression indicates that tumor cells did not activate astrocytes’ tumor-suppressive functions but instead promoted tumor-supportive properties, as evidenced by significant upregulation of STAT3 signaling following tumor cell exposure." (PMID 40149331, 2025). "In addition, CCL5 positivity was also an independent prognostic parameter in the MIBC subgroups, i.e., for OS, DSS, and RFS in both the tumor stage 3 + 4 and no chemotherapy subgroups." (PMID 38928033, 2024). "However, following NK cells infusion, there was no change in the relative mRNA expression of CCL5 and XCL1 in the tumor tissues." (PMID 38725070, 2024). "Interestingly, while TWEAK secretion is not high in PDAC tumor cells, macrophages can respond to tumor cell-secreted CCL2, activate and secrete CCL5, and significantly upregulate TWEAK expression and secretion in tumor cells via the TRAF6/NF-κB pathway." (PMID 38982491, 2024). "Further, 4-culture tumor spheroids decreased the concentrations of T-cell chemoattracting cytokines, i.e., CCL4, CCL5, and CXCL9, when compared with the non-cancerous spheroids, revealing a critical immunosuppressive feature of the different types of cells forming the tumor spheroids." (PMID 37519820, 2023). "As a result, the truncated non-signaling CD19 and BCMA could be delivered to the tumor cell surface as CAR targets and CCL5 would be released into the TEM to infiltrate CAR T cells before oncolytic virus-mediated tumor lysis." (PMID 36353540, 2022).
tumor (continued). "When compared to exosomes from tumor cells without heat stress (TEX), heat-stressed tumor cell-derived exosomes (HS-TEX) had more chemokines (CCL2, CCL3, CCL4, CCL5, and CCL20), HSPs (HSP60, HSC70, HSP70, and HSP90), and adhesion molecules (e.g., CD54 and CD86)." (PMID 35158999, 2022). "On the basis of the principle of ceRNA hypothesis, C22orf34, RFPL1S, and LINC00996 shared same expression patterns as CXCL10, CXCL9, CCL5, FCGR3A, and CCR2, all which were upregulated in tumor tissues of PTC with HT compared with those without HT." (PMID 36266640, 2022). "Although CCL5 does not seem to mediate direct chemotactic effects on CD8+ T cells, its absence in orthotopic CRC tumor models interestingly resulted in the marked accumulation of intratumoral effector CD8+ T cells and in significantly reduced tumor growth." (PMID 36428508, 2022). "The quantitative PCR results were consistent with the transcriptome results, showing that the expression of CCL2, CCL3, CCL5, and CXCL9, but not CCL17 or CCL22, was markedly higher in 1.5 mg/kg AAGL-treated tumor-bearing mouse livers than in those of control mice." (PMID 33710817, 2021). "When CCL5 was overexpressed (CCL5high) in human BM1 or mouse LMB TNBC cells, we observed a slight but not significant increase in EV secretion from comparable tumor cell numbers." (PMID 34298673, 2021). "When the effect of CCL5 was blocked by TAK‐779, the HIF‐1α‐expressed fibroblasts CM could not promote the growth of tumour cells." (PMID 33943003, 2021). "Notably, the expression levels of CD3E, CCL5, CXCR6 and LCK in tumor samples and adjacent non-tumor samples were markedly different, and the results were consistent with the results of the analysis using TCGA." (PMID 34218795, 2021). "Cytokine profiling of conditioned media from the co-culture of 3-D MVNs with tumor spheroids revealed a cooperative production of multiple chemo-attractants downstream of STING such as CXCL10, CCL5, and CCL2, which was surprisingly independent of cancer cell STING." (PMID 33013881, 2020). "A comparative immunohistochemical (IHC) analysis of CCL5 expression in CRC samples between drinkers and nondrinkers revealed that the former displayed higher levels of CCL5 in both the tumors and the adjacent non-tumor tissues." (PMID 29872080, 2018). "Accordingly, we analyse the cytokine expression changes (more than 1.5 log2, 2.8 fold, p < 0.05, t-test) between No take and Take tumours and found a large series of chemokine/cytokine overexpressed in the No take samples, among them IFNG, CXCL13, CXCl9, CXCl11, CXCL10 and CCL5." (PMID 28588211, 2017). "Notably, when cells derived from tumours harvested from MMTV-PyMT.CCR5−/− mice are treated with CCL5, we observe no enhancement in glucose uptake, in support that CCR5 is the receptor mediating this effect." (PMID 27335323, 2016). "In our study, CCL5 and CXCL10 were more highly expressed in cancerous tissues than in marginal sites; the chemokines' expression was not affected by patients' age, gender, tumor differentiation, or clinical TNM stages, except that CCL5 was further upregulated in clinical T3-T4 stages." (PMID 26317795, 2015). "CCK assays showed that Ccl5 knockdown could not influence the cell proliferation phenotype of shKmt5c in vitro, suggesting that CCL5 may mainly contribute to the role of KMT5C in regulating the tumor immune microenvironment." (PMID 40126333, 2025). "We found increased accumulation of CCL5+ CD8+ T cells and to a lesser extent CCL5+ NKT cells in OVX mice injected with these cells and estrogen supplementation in OVX mice reversed these trends, suggesting that the changes observed in the IME were not tumor-type specific." (PMID 39007345, 2024).
tumor (continued). "Notably, the transfer of CART19-28z SNX9 KO was accompanied with increased serum levels of anti-tumor effector molecules IFNγ, Perforin, and Granulysin, while we detected a decrease in IL10 and IL6 (human CCL5 could not be detected in the serum)." (PMID 36732507, 2023). "In addition, ACKR2 expression was correlated to the expression of its counterpart ligand, i.e., CCL2, but not CCL5 and CCL8, suggesting that ACKR2 downregulation increases CCL2 in the tumor microenvironment to recruit more inflammatory cells and promote inflammation." (PMID 35677043, 2022). "Furthermore, ZNF281 in CAFs upregulated CCL2 and CCL5 rather than VEGFA expression, which stimulated angiogenesis and vascular permeability through P38 MAPK signaling in endothelial cells, consequently contributing to lung PMN formation in tumor metastasis." (PMID 36438499, 2022). "However, we found that autophagy inhibition by CQ or ULK1 depletion did not increase the expression of CCL5 or CXCL10 in NSCLC cells, suggesting that autophagy inhibition could not promote the infiltration of NK cells into NSCLC tumor." (PMID 35002511, 2022). "However, we failed to reduce metastases in mice by using single CCR5/CCL5 antagonist Maraviroc, which may be the multiple stimulation of TME that contributes to tumor progression." (PMID 30200999, 2018). "Interestingly, ASPP2 KD, but not overexpression, increased the expression of CCL2, CCL5, and TNF-α and enhanced their secretion, which may promote macrophage recruitment to tumor tissues and support multiple aspects of tumor progression." (PMID 30389910, 2018). "However, the differences in CCL5 and CCL4 expression between IL-32–treated tumors from WT and Batf3–/– mice were not statistically significant, suggesting that DC are not exclusively responsible for the increased tumor chemokine levels in response to IL-32 treatment." (PMID 32841222, 2020).
infection (958 papers, 2004 to 2026). The state of being infected such as from the introduction of a foreign agent such as serum, vaccine, antigenic substance or organism. "We found that maSARS-CoV-2–infected mice had increased production of G-CSF, IL-12 p40, CCL2, and CCL5, which are often linked to monocyte recruitment, a prominent feature of this infection." (PMID 40854598, 2025). "Low gene expression levels and low serum concentration of CCL5 in the early stages of an iGAS infection were associated with a more severe disease course." (PMID 38865072, 2025). "This is likely not a GAS specific association, and further studies are warranted to outline the behavior of CCL5 and other associated genes in the very first days of symptoms in iGAS infections as well as other bacteremic infections." (PMID 38865072, 2025). "MC were shown to be susceptible for productive infection and to secrete the chemokine CCL-5, which recruits antiviral CD8 T cells to the lungs and thereby improves the immune control of pulmonary infection." (PMID 35563708, 2022). "Infection associated receptor encoding genes include CCR1 (encoding a receptor for CCL5), CRLF2 (cytokine receptor like factor 2), IL10RA, TLR2, CD2, CD48 and IL7R." (PMID 35061738, 2022). "Peptides TAT-I24 and TAT-M26, which were able to cause significant inhibition of ie1 gene expression, also caused a significant reduction of Ifit1, Ccl7 and Ccl5 expression 2 h post-infection." (PMID 35806257, 2022). "Chemokines produced during the course of RSV infection have been linked to disease severity, including CXCL1, CCL2 and CCL5, either in murine models of infection or in patients." (PMID 32107411, 2020). "In contrast, during infection, the opposite relationship was frequently found, with IL-4, IL-13, CCL5, CCL20 and CCL24 levels associated with less severe reductions in both FVC and FEV1." (PMID 30463560, 2018). "There was a T allele dependency on IL-7, IL-8, IL-17, and CCL5 serum level in the patients during the acute phase of the infection." (PMID 28512644, 2017). "Asthmatic bronchial epithelial cells have a deficient IL-6 and CCL5 induction in response to rhinovirus-16 infection compared with cells from healthy volunteers." (PMID 28842514, 2017). "CCL5 responses are directed by WNV, DENV, and Tick-borne encephalitis virus (TBEV) infection of brain ECs, and CCL5 induction is associated with increased WNV and TBEV pathogenesis." (PMID 28698279, 2017). "Their expression levels, in combination with the availability of their respective ligands CCL2 and CCL5, have been linked to recruitment of activated immune cells at the site of infection in the CNS." (PMID 27313404, 2016). "SeV-induced expression of IFN-β, CXCL10, Mx1 and CCL5 in OPN-deficient macrophages was also restored upon infection with lentivirus containing the C-terminal fragment of iOPN." (PMID 27026194, 2016). "The viral activation of MC was associated with a wave of CC chemokine ligand 5 (CCL5) in the serum of C57BL/6 mice that was MC-derived as verified by infection of MC-deficient KitW-sh/W-sh “sash” mutants." (PMID 24763809, 2014). "CCL5 plays a key role in the antimycobacterial immune response by recruiting mononuclear cells to the site of infection, study has shown that the -403 A CCL5 allele is associated with lower serum level of CCL5." (PMID 24015211, 2013). "CCL5 expression correlates with resistance, and blockade of CCL5 rendered mice more susceptible to infection." (PMID 20368974, 2010). "Despite the lack of microglia or other immune cells in this system, the levels of several proinflammatory cytokines were increased upon infection by all three EVs, including cytokines previously associated with EV neuropathogenesis such as IL-6, IL-8 and CCL5 (RANTES)." (PMID 41332624, 2025). "Conversely, SNPs linked to decreased protein levels of CCL5/RANTES may be associated with increased susceptibility to infection." (PMID 37766364, 2023).